SPRR1B (small proline rich protein 1B)
Diseases named in the same sentence as SPRR1B in open-access papers:
SPRR1B is named in the same sentence as 35 diseases in open-access papers, as found by Europe PMC text mining. Sharing a sentence is not in itself a finding about the gene and the disease. The quoted sentences say what the papers report.
melanoma (10 papers, 2008 to 2025). A malignant, usually aggressive tumor composed of atypical, neoplastic melanocytes. "The results showed that the highly expressed prognostic risk gene SPRR1B had significantly worse OS (HR: 5.5, P=0.001) in the melanoma immunotherapy cohort of Hugo." (PMID 36817451, 2023). "Overall, this systematic meta-analysis of gene profiling was a step forward in the investigation of the mechanisms underlying melanoma's metastasis, and the role of SPRR1B, SPRR2B, TGM1, CDSN, and IVL in keratinocyte differentiation GO term needs to be further studied." (PMID 35003328, 2021). "SPRR1B was also found to be associated with the prognosis of melanoma." (PMID 34737950, 2021). "We used Transwell chamber test to detect the effect of SPRR1B gene on the migration ability of two human melanoma cell lines." (PMID 34737950, 2021). "We demonstrated for the first time that SPRR1B can promote the proliferation, invasion and migration of melanoma cells, providing a new perspective on the combined role of m6A regulatory factors and other m6A-related genes in cutaneous melanoma." (PMID 34737950, 2021). "Our results provide a new view for the comprehensive action of m6A regulatory factors and other m6A related genes in skin melanoma, and it is found for the first time that SPRR1B can promote the proliferation, invasion and migration of melanoma cells." (PMID 34737950, 2021). "The results of TMA also confirmed that IGF2BP3 was significantly up-regulated in melanoma, and also confirmed that SPRR1B was significantly down-regulated in metastatic cancer before tumor invasion and metastasis." (PMID 34737950, 2021). "At the same time, it was found that the abnormal up-regulated expression of SPRR1B before metastasis would lead to poor prognosis of melanoma." (PMID 34737950, 2021). "SPRR1B promotes the proliferation, invasion and migration of human melanoma cells." (PMID 34737950, 2021). "SPRR1B knockout inhibited the proliferation of human melanoma cells." (PMID 34737950, 2021). "SPRR1B promoted the proliferation, invasion, and migration of human melanoma cells." (PMID 34737950, 2021). "The expression of SPRR1B in A375, SK-MEL-2, A2058 and SK-MEL-28 human melanoma cell lines was detected by real-time fluorescence quantitative PCR." (PMID 34737950, 2021). "After SPRR1B gene knockout, we used CCK-8 proliferation assay to detect the number of human melanoma cells A375 and SK-MEL-2 and draw the growth curve." (PMID 34737950, 2021). "Some of the genes, such as LOR, SPRR1B, and IVL, were even undetectable in metastatic melanoma tissue." (PMID 35003328, 2021). "But the report of SPRR1B, SPRR2B, TGM1, CDSN, and IVL in melanoma was a gap." (PMID 35003328, 2021).
lung adenocarcinoma (6 papers, 2021 to 2025). A carcinoma that arises from the lung and is characterized by the presence of malignant glandular epithelial cells. "However, the specific downstream targets of SPRR1B in lung adenocarcinoma, the epigenetic regulatory mechanism, and its association with the immune microenvironment are still not fully elucidated." (PMID 40568599, 2025). "In lung adenocarcinoma, the expression of SPRR1B is significantly up-regulated and is closely related to the poor prognosis of patients." (PMID 40568599, 2025). "To clarify the changes in the expression of SPRR1B in lung adenocarcinoma cell lines, we used five different lung adenocarcinoma cell lines (A549, PC9, H1975, H1650, H1299) and a normal human bronchial epithelial cell line (BEAS‐2B)." (PMID 33501784, 2021). "SPRR1B knockdown can inhibit lung adenocarcinoma cell proliferation, migration, and invasion, and it induced the G2/M phase arrest in vitro." (PMID 33501784, 2021). "SPRR1B was found to be highly expressed in lung adenocarcinoma cells compared with that in normal bronchial epithelial cells." (PMID 33501784, 2021). "SPRR1B has been validated in lung adenocarcinoma and included in a PC model." (PMID 40574800, 2025). "In addition, SPRR1B was a prognostic or diagnostic biomarker for various malignancies such as PAAD, lung adenocarcinoma, metastatic cutaneous melanoma, and oral squamous cell carcinoma among others." (PMID 36817451, 2023). "It has been well known that SPRR family molecules played important functions in the progression of many diseases, so SPRR families, especially SPRR1B, may be potential predictive biomarkers of lung adenocarcinoma." (PMID 35256894, 2022). "Further investigation will determine whether RASSF4 is the direct target of SPRR1B in lung adenocarcinoma, and further studies are needed to discover the molecular mechanisms involved." (PMID 33501784, 2021). "SPRR1B was determined to be a prognostic marker of lung adenocarcinoma." (PMID 33501784, 2021). "SPRR1B was determined to be a prognostic marker of lung adenocarcinoma, based on Oncomine meta‐analysis and Kaplan–Meier analysis, as its expression increased in lung adenocarcinoma tissues and cell lines." (PMID 33501784, 2021). "In conclusion, SPRR1B is highly expressed in lung adenocarcinoma, may predict poor prognosis, and is involved in diverse cell biological functions." (PMID 33501784, 2021). "The western blot results showed that the expression level of phosphorylated MAP kinase in SPRR1B knockdown cells were significantly downregulated, which implies that SPRR1B may affect the phenotype of lung adenocarcinoma cells by regulating the MAP kinase signaling pathway." (PMID 33501784, 2021). "In addition, silencing of SPRR1B could inhibit the cell proliferation, invasion, and migration of lung adenocarcinoma cells, but induced cell apoptosis and G2/M phase arrest in vitro." (PMID 33501784, 2021). "Our findings demonstrate that SPRR1B may function as a prognosis predictor in lung adenocarcinoma." (PMID 33501784, 2021). "In recent years, several studies have suggested that genes such as SPRR1B, MFI2, LIPK, GREB1L, and GPR115 may play a potential role in lung adenocarcinoma (LUAD)." (PMID 40568599, 2025).
oral squamous cell carcinoma (5 papers, 2020 to 2023). "Mechanistically, overexpression of Sprr1b in human oral squamous cell carcinoma cell lines has been found to impact MAP kinase signaling but none of these candidates have been studied in T cells." (PMID 38143765, 2023). "Previous studies have suggested that SPRR1B is overexpressed in oral squamous cell carcinoma stem‐cell‐like cells, thereby affecting cell growth." (PMID 33501784, 2021). "Previous studies have shown that SPRR1B gene is overexpressed in oral squamous cell carcinoma stem cell-like cells, which affects cell growth." (PMID 34737950, 2021).
metastatic melanoma (4 papers, 2020 to 2023). A melanoma that has spread from its primary site to another anatomic site. "At the same time, some studies have shown that the expression of SPRR1B is down-regulated in metastatic melanoma." (PMID 34737950, 2021).
head and neck squamous cell carcinoma (3 papers, 2016 to 2023). A squamous cell carcinoma that arises from any of the following anatomic sites: lip and oral cavity, nasal cavity, paranasal sinuses, pharynx, larynx, and salivary glands. "In head and neck squamous cell carcinoma (HNSCC), SPRR1B affects HNSCC angiogenesis by targeting MDA‐9/Syntenin, thereby affecting tumor invasion and differentiation." (PMID 33501784, 2021). "In head and neck squamous cell carcinoma, MDA-9 colocalized with VEGFR1 and regulated the expression of SPRR1B and VEGFR1." (PMID 27863394, 2016).
cutaneous melanoma (2 papers, 2020 to 2021). A primary melanoma arising from atypical melanocytes in the skin. "Survival analysis was performed on TCGA cutaneous melanoma clinical data set according to the expression level of SPRR1B." (PMID 34737950, 2021). "The high expression of SPRR1B has a poor prognosis and plays an important role in the prognostic model, which shows its potential as a good prognostic marker for cutaneous melanoma." (PMID 34737950, 2021). "SPRR1B gene enrichment analysis showed that the high expression group enriched the first ascorbic acid and alginate pathway, and it was found that the metabolites of ascorbic acid and alginate were different before and after skin melanoma metastasis, which may be related to the metastasis progress." (PMID 34737950, 2021).
lung carcinoma (2 papers, 2020 to 2021). "The result of GSEA and immunoblotting revealed that SPRR1B activated the MAPK signaling pathway involved in the proliferation and metastasis of lung cancer." (PMID 33501784, 2021). "Oncomine also showed, in our analysis, that SPRR1B and SPRR2D are overexpressed in lung cancer." (PMID 33501784, 2021). "Accordingly, we found that the expressions of SPRR1B and SPRR2D in multiple tumor data sets were higher in tumor tissues than in normal tissues (72 vs. 16 and 62 vs. 22, respectively), and the data sets with high expression in lung cancer were significantly more than those of other types of cancer." (PMID 33501784, 2021).
psoriasis (2 papers, 2011 to 2021). An autoimmune condition characterized by red, well-delineated plaques with silvery scales that are usually on the extensor surfaces and scalp. "Results suggested that the higher the expression of CXCL9 and SPRR1B, the greater the risk of psoriasis." (PMID 34134787, 2021). "Among them, high expression of CXCL9 and SPRR1B may be risk factors for psoriasis." (PMID 34134787, 2021). "Consistent with our analysis, SPRR1B has also been identified as a potential biomarker of psoriasis by other studies." (PMID 34134787, 2021). "The AUC values of hub genes were all greater than 0.7, which may have the ability to judge psoriasis, especially SPRR1B." (PMID 34134787, 2021). "Importantly, CXCL9 and SPRR1B, as well as methylation markers TGM6 and S100A9, have an impact on the risk of psoriasis." (PMID 34134787, 2021). "In all five mouse phenotypes, there was increased expression of S100a9, Lcn2, S100a8, Sprr1b, Mpzl2, Has3, as well as decreased expression of Tppp, Stxbp6, and Cldn23, and each of these effects is consistent with characteristic expression patterns in clinical psoriasis." (PMID 21483750, 2011). "CXCL9, SPRR1B, TGM6 and S100A9 may be potential targets for the diagnosis and treatment of psoriasis." (PMID 34134787, 2021).
pterygium (2 papers, 2009 to 2021). A wedge-shaped fibrovascular lesion arising from the bulbar conjunctiva and extending to the cornea. "An early microarray study identified SPRR3, SPRR1A, SPRR1B and IVL from the cornification subcategory as upregulated genes in pterygium." (PMID 34769520, 2021). "Other up-regulated proteins like small proline rich protein 1B (SPRR1B), CD24, S100 calcium binding protein, SPARC, TFF1, SPRR1B and SERPINB13 also govern the wound healing process and cornification of epithelium, again, supporting the hypothesis of aberrant wound response in pterygium." (PMID 19272163, 2009).
asthma (1 paper, 2021). "While the roles of SPRR1B and SPRR3 in asthma are unclear, it has been shown that the members of the SPRRs family SPRR2A and SPRR2B are upregulated in an IL-13-dependent manner in an allergen-induced asthma model." (PMID 35126350, 2021).
breast carcinoma (1 paper, 2014). "Gain of 1q in cancer, specifically in breast cancer has previously been described but is impressively evidenced in this study by frequent co-amplification of the SYK-regulated SPRR1A, SPRR1B, MUC1, RAB25, and ADAM15, genes located within chromosome 1q." (PMID 24523870, 2014).
cervical intraepithelial neoplasia (1 paper, 2023). "SPRR1B is a proline-rich molecule that has been associated with cervical intraepithelial neoplasia." (PMID 36807337, 2023).
cholesteatoma (1 paper, 2012). A pathologic process characterized by the proliferation of keratinizing squamous epithelium resulting in the accumulation of keratin and cells in the middle ear and/or mastoid. "Our results indicate that SPRR1B expression is up-regulated in cholesteatoma compared to skin (logFC 3)." (PMID 23285167, 2012). "Real-time PCR of PI3, SPRR1B, LCN2 (lipocalin 2), MMP1, MMP9, MMP10, MMP12, SPP1, GJB2, Bcl-xl (BCL2L1), cIAP2 (BIRC3), S100A7A (koebnerisin), S100A9, SERPINB3, CEACAM6, KRT6B and SERPINB4 revealed that the expression levels of these proteins were higher in cholesteatoma than in external canal skin." (PMID 23285167, 2012).
conjunctiva disease (1 paper, 2021). "As a member of the SPRR family, SPRR1B has been studied in various diseases, including cancers, conjunctiva disease,20and cutaneous disease." (PMID 33501784, 2021).
endometrial cancer (1 paper, 2023). Primary or metastatic malignant neoplasm involving the endometrium (mucous membrane that lines the endometrial cavity). "A four-marker panel comprising of SPRR1B, CRNN, CALML3 and TXN predicted endometrial cancer with an AUC of 0.80 (0.71–0.88)." (PMID 36807337, 2023). "Urine SPRR1B, S100A7, CALML3 and TXN were also found to have potential as endometrial cancer biomarkers." (PMID 36807337, 2023).
lung squamous cell carcinoma (1 paper, 2021). "Moreover, the available studies showed that SPRR1B was overexpressed in lung squamous cell carcinoma tissue." (PMID 33501784, 2021).
lymphoid cancers (1 paper, 2023). "SPRR1B may be oncogenic in epithelial cells, while EHHADH has also been linked with non-lymphoid cancers." (PMID 38143765, 2023).
metastatic cancers (1 paper, 2021). A carcinoma which has spread from the original site of growth to another anatomic site. "Among the first 20 down-regulated genes in metastatic cancer, the down-regulated genes in PPI network are mainly KRT family members, SPRR1B genes, and so on." (PMID 34737950, 2021). "We observed multiple occurrences of SPRR1B, one of the most significantly down-regulated genes in the IGF2BP3 overexpression group, and one of the most significantly down-regulated genes in metastatic cancer." (PMID 34737950, 2021).
oral cancer (1 paper, 2025). "In oral cancer stem cells, overexpression of small proline-rich protein 1B (SPRR1B) significantly suppresses RASSF4 protein levels, thereby inhibiting MAP kinase signaling-driven proliferation." (PMID 41007433, 2025).
skin squamous cell carcinoma (1 paper, 2014). A carcinoma arising from the squamous cells of the epidermis. "Loss of SPRR1B was associated with the development of bronchial epithelial cells malignancy and skin squamous cells carcinomas." (PMID 25593999, 2014).
squamous cell carcinoma (1 paper, 2006). A carcinoma arising from squamous epithelial cells. "Low SPRR expression has been associated with squamous cell carcinoma, whereas high expression of SPRR1B enhanced G0-arrest resulting in growth arrest." (PMID 16420688, 2006).
tumor (16 papers, 2012 to 2025). "Moreover, the risk gene SPRR1B was highly expressed in the disease state of tumor recurrence/progression." (PMID 36817451, 2023). "Studies have shown that SPRR1B is abnormally high expressed in a variety of solid tumors (such as esophageal cancer, head and neck squamous cell carcinoma), and promotes tumor invasion and metastasis by activating signaling pathways such as EGFR/MAPK." (PMID 40568599, 2025). "In contrast, SPRR1B significantly increased accumulation of adoptively transferred T cells in both the tumor (2.8-fold) and spleen (6.6-fold)." (PMID 38143765, 2023). "Remarkably, silencing SPRR1B inhibited the regulatory functions of miR-330-5p knockdown on malignant phenotype in BC cells, thereby inhibiting the tumour-promoting effect of HAGLROS." (PMID 35664787, 2022). "The resulting impact on HNSCC tumor development is mediated through the regulation of various squamous differentiation, proliferation and angiogenic factors including SPRR1B and VEGFR1." (PMID 25593999, 2014). "Our observation that MDA-9/Syntenin overexpression was evident in pre-neoplastic stages supports a model in which MDA-9/Syntenin mediated down-regulation of SPRR1B is an early event preventing terminal differentiation thereby aiding in tumor progression." (PMID 25593999, 2014). "Further mechanistic studies have found that SPRR1B may enhance the migration ability and drug resistance of cancer cells by regulating cytoskeletal remodeling, matrix metalloproteinase (MMPs) secretion, and tumor microenvironment interaction." (PMID 40568599, 2025). "SPRR1B may be related to tumor cell growth by regulating MAP kinase signal transduction pathway." (PMID 34737950, 2021). "PCR results showed elevated expression of GREB1L, MFI2, SPRR1B, GPR115 and LIPK mRNA in LUAD tumor tissues." (PMID 40568599, 2025). "Integrated analysis of GTEx (normal, n = 171) and TCGA (tumor, n = 179) datasets revealed higher expression of CHST11, SLC16A1, RHOF, MAN1C1, SPRR1B, and ANO6 in tumors." (PMID 41346619, 2025). "Differential gene analysis revealed 319 genes upregulated in tumor-derived fibroblasts, such as DCN and SFRP4, and 214 genes upregulated in cancer cells, such as SPRR1B and SLURP2." (PMID 36357663, 2022). "SPRR1B is co-expressed with keratin genes (KRT14, KRT6B), which may promote tumor invasion by regulating EMT." (PMID 40568599, 2025). "Importantly, adoptive transfer of T cells overexpressing gain-of-function candidates (AAK1ΔN125, SPRR1B, and EHHADH) into tumor-bearing mice resulted in increased T cell infiltration into tumors." (PMID 38143765, 2023). "In addition, epithelial cell differentiation regulation-related genes, such as AKR1B1, SPRR1B, and keratin genes KRT6A, KRT19, and KRT17 were also highly expressed in mixed-lineage tumor cells." (PMID 35962452, 2022). "While SPRR1B may improve overall engraftment and infiltration, the infiltration does not appear to be tumor specific, which may decrease translational interest in this gene candidate." (PMID 38143765, 2023).
cancer (13 papers, 2014 to 2025). A tumor composed of atypical neoplastic, often pleomorphic cells that invade other tissues. "Related studies have revealed that the SPRR1B is closely associated with the tumorigenesis and progression of carcinoma by regulating the epithelial-mesenchymal transition (EMT) and participating in the Ras/MEKK1/MKK1 and MAPK signalling pathways." (PMID 35664787, 2022). "A pan-cancer analysis revealed that SPRR1B was a significant biomarker of cancer stemness that used for predicting immunotherapy response." (PMID 40574800, 2025). "This study provides rationale for investigating all top gene candidates, and especially AAK1ΔN125, EHHADH, and SPRR1B, for therapeutic consideration in cancer immunotherapy." (PMID 38143765, 2023). "However, Sprr1b has also been demonstrated to be overexpressed in multiple types of cancer with poor prognosis." (PMID 37809094, 2023). "SPRR1B, a cytosolic protein of keratinocytes, is a marker of highly differentiated epithelial cells and has been reported as a potential target for predicting immunotherapeutic response in pan-cancer." (PMID 37180113, 2023). "Notably, SPRR1B knockdown reversed the malignant phenotypes of BC cells promoted by decreasing miR-330-5p, thereby inhibiting the cancer-promoting effect of HAGLROS." (PMID 35664787, 2022). "An adjusted (Tukey) box-plot analyses showed evidence of lower concentrations of SPRR1B, CRNN, TXN and FABP5 in cancers compared to controls." (PMID 36807337, 2023). "In addition, we also identified 6 upregulated genes not typically associated with cancer (ARC, C1orf167, CNGA3, KRT75, SPRR1B, STUM)." (PMID 38038766, 2024).
adenocarcinoma (1 paper, 2021). A common cancer characterized by the presence of malignant glandular cells. "In our research, we demonstrated that SPRR1B is highly expressed in adenocarcinoma and is correlated with worse prognosis." (PMID 33501784, 2021).
SPRR1B also shares sentences with these, for which no sentence is quoted: Stroke (2 papers); anal tumors (1); Bladder Cancer (1); bladder tumour (1); cervical cancer (1); esophageal cancer (1); infection (1); keratoconus (1); larynx cancer (1); pancreatic cancer (1); skin infection (1).